STAT3 (signal transducer and activator of transcription 3)
Diseases named in the same sentence as STAT3 in open-access papers (continued):
Sharing a sentence is not in itself a finding about the gene and the disease.
brain cancer (21 papers, 2010 to 2025). A primary or metastatic malignant neoplasm affecting the brain. "Recent studies have suggested STAT3 signaling to be directly associated with the progression of several tumors such as brain cancer, breast cancer, prostate cancer, and lung cancer." (PMID 32971907, 2020). "Our finding demonstrates that STAT3 might serve as a diagnostic and therapeutic target for certain types of cancer, including lung, ovarian, gastric, blood and brain cancers." (PMID 29423040, 2018). "STAT3 activity plays important roles in pathogenesis of many cancers, including breast, head and neck, prostate and brain cancers." (PMID 33448640, 2020). "Taken together, these data suggest that pimozide has the ability to inhibit the growth of brain cancer in vitro and in vivo by inhibiting STAT3, leading to induced autophagy-mediated apoptosis." (PMID 32971907, 2020). "The reduced expression of STAT3 with pimozide treatment resulted in increased autophagy, which in turn enhanced apoptosis in brain cancer cells." (PMID 32971907, 2020). "The hyperactivation of STAT3 in brain cancer cells has been strongly attributed to the evasion of apoptosis." (PMID 32971907, 2020). "Our results showed that inhibiting STAT3 induces autophagy, which in turn increases the apoptosis in brain cancer cells." (PMID 32971907, 2020). "We observed that pimozide significantly suppressed the growth of brain cancer cells by modulating STAT3-mediated autophagy signaling." (PMID 32971907, 2020). "Several studies have confirmed the overexpression of STAT3 in various brain cancers and its role in the regulation of inflammatory mediators." (PMID 28346397, 2017). "Though the detection rates obtained from retrospective, immunohistochemistry-based studies varied (9%–83%), STAT3 over-activation is considered to be a precipitating factor in most brain cancers." (PMID 28346397, 2017). "STAT3 activation alone was insufficient to induce brain cancer formation, but co-expression of STAT3 with PDGF-B in a transgenic mouse model resulted in efficient glioma multiforme formation." (PMID 27259262, 2016). "STAT3 signaling plays a pivotal role in regulating differentiation and proliferation of neuronal cells and its activation is closely related with brain cancer formation." (PMID 28035977, 2016). "In mammary and brain cancer cells [MMF + ruxolitinib] significantly inhibited the phosphorylation of STAT3 and STAT5 after 12h of treatment by > 50%, as would be expected based on the declared kinase specificity of ruxolitinib (p < 0.05)." (PMID 26981780, 2016). "However, it was later found that this protein can serve as an oncogenic co-activator of estrogen receptor (ER), androgen receptor (AR) and the STAT3 signaling pathway in breast, prostate, and brain cancers, respectively." (PMID 32660118, 2020). "We found that STAT3 was more frequently overexpressed in lung, ovarian, gastric, blood and brain cancers than their normal tissues and its expression might be negatively related with the prognosis." (PMID 29423040, 2018). "Furthermore, several studies have demonstrated that the inhibition of STAT3 led to radiosensitization of different cancer cell lines including breast, colorectal, uterine, head and neck and brain cancers." (PMID 29423098, 2018). "STAT3 over-activation was also observed in anaplastic astrocytomas and other brain cancers." (PMID 28346397, 2017). "Several studies have found a persistent STAT3 activity in various brain cancers." (PMID 28346397, 2017). "In particular, STAT3 phosphorylation upregulates BNIP3 expression and contributes to the survival of brain cancer cells via autophagy." (PMID 40021617, 2025). "The STAT3 inhibitor tested was WP1066, a compound developed for hematologic malignancies, currently in a Phase I clinical trial for malignant brain tumors in children." (PMID 38935814, 2024).
brain cancer (continued). "STAT3 CNA predicted dysfunctional T cell phenotype and worse prognosis in stomach and lymphoma cancers while predicting a good prognosis of endometrial and brain cancer." (PMID 33668805, 2021). "Our results indicated that knocking down STAT3 using shRNA does not significantly induce autophagy on its own in brain cancer cells." (PMID 32971907, 2020). "Moreover, STAT3 expression has been shown to correlate with PDGF-B expression, a well-described initiator of brain cancer." (PMID 27259262, 2016).
fungal infections (21 papers, 2011 to 2026). "Impaired Th 17 cell differentiation is an immune defect consistently found in the STAT3 Job’s syndrome mutation and this mutation impairs protection against invasive fungal infections including histoplasmosis." (PMID 34209280, 2021). "Of interest, patients with loss-of-function STAT3 mutations or with gain-of-function STAT1 mutations show similar susceptibility to fungal infections." (PMID 31998303, 2019). "It is also noted that endemic mycoses frequently cause disseminated disease including histoplasmosis, Coccidioides, and Cryptococcus, requiring prophylaxis for high-risk exposure in all patients identified with a STAT3 LOF gene mutation." (PMID 41164159, 2025). "Furthermore, APECED syndrome with biallelic mutations in the AIRE gene and HIES with dominant-negative mutations in the STAT3 gene are also characterized by increased susceptibility to fungal infections, which may manifest as CMC." (PMID 38327523, 2024). "In humans, loss-of-function mutation in the Signal Transducer and Activator of Transcription 3 (STAT3) gene is frequently associated with susceptibility to bacterial as well as fungal infections including aspergillosis, although its pathogenesis remains largely unknown." (PMID 32047500, 2020). "For example, patients with Jobs syndrome, also known as signal transducer and activator of transcription 3 (STAT3) deficiency, can manifest with high blood IgE levels and are more susceptible to fungal infection." (PMID 34682263, 2021). "We analyzed all the exons encoding caspase recruitment domain-containing protein 9 (CARD9) and signal transducer and activator of transcription 3 (STAT3), which have previously been linked to invasive fungal infections." (PMID 31752715, 2019). "IL‐6 is a pleiotropic cytokine that signals through STAT3 and is evidently critical in protection against staphylococcal and fungal infections." (PMID 27957331, 2016). "These cases suggest increased risk of disseminated fungal infection with endemic mycoses in HIES patients, raising the possibility that STAT3 has a role in intracellular infection." (PMID 22126402, 2011). "Fedratinib's immune mechanism is thought to inhibit the phosphorylation of STAT3 and STAT5, which could correlate with a STAT3 LOF gene mutation, challenging the idea that endemic mycoses are associated with STAT3 LOF mutations." (PMID 41164159, 2025). "STAT3 gene mutation was identified to be the cause of the autosomal dominant form of Hyper IgE Syndrome (AD-HIES) that results in impaired Th17 cell differentiation and increased susceptibility to bacterial and fungal infections, especially Candidiasis." (PMID 39229272, 2024). "One of those markers is Signal transducer and activator of transcription 3 (STAT3), a member of the STAT protein family and an important transcription activator has been found to have an important role in invasive fungal infections as it is associated to the T-helper cell 17 (Th17) pathway." (PMID 30687264, 2018). "A loss in the homeostasis of STAT3-mediated Th17 polarization and a lack of IL-17A and Th17 secreted cytokines parallel the Th1 overactivation and lead to an imbalanced defense against fungal infections." (PMID 36826612, 2023). "In conclusion, our study demonstrated that C. neoformans infection stimulates the development of Th17 cells to produce IL-17 by activating the STAT3-dependent signal pathway, and IL-17 could be a potential biomarker of and STAT3 a checkpoint of targeted therapies for fungal infection." (PMID 35720334, 2022). "STAT3 hyper IgE syndrome (STAT3-HIES) is a rare inborn error of immunity characterized by chronic eczema, recurrent bacterial and fungal infections, markedly elevated serum IgE levels, and a broad spectrum of skeletal, dental, vascular, and gastrointestinal manifestations." (PMID 42221228, 2026).
gastritis (21 papers, 2012 to 2025). Inflammation of the stomach. "Among them, IL-6 activates the STAT3 pathway, of which the activation is correlated with the H. pylori-associated gastritis and gastric cancer." (PMID 35013458, 2022). "We also explored possible association between Ser727 phosphorylation of STAT3 and autophagy in a H. pylori-induced murine gastritis model." (PMID 32973302, 2020). "In addition, the high expression of BHLHE40 in gastric epithelial cells increased the production of CXCL12 by interacting with p-STAT3 in Helicobacter pylori-associated gastritis, which further aggravated the development of gastritis." (PMID 34917665, 2021). "Studies have shown that the phosphorylation level of STAT3 in the gastric mucosa was upregulated during HP infection, and the activation level of STAT3 was related to the occurrence and development of HP-related gastritis and cancer." (PMID 35958524, 2022). "Because gastric carcinogenesis results from prolonged gastritis due to long-term Helicobacter infection, we investigated the role of STAT3 in gastric carcinogenesis using Stat3Δgec mice with long-term Helicobacter infection." (PMID 29849601, 2018). "In this study, we investigated the activation of STAT3 using Stat3Δgec mice; however, other factors are involved in Helicobacter-induced gastritis/carcinogenesis, for example, stromal cells have been prominently increased in infected gastritis." (PMID 29849601, 2018). "Subsequently, IL-23 that is increased in patients with H. pylori gastritis will promote Th17 cell proliferation via the STAT3 pathway." (PMID 25569625, 2015). "Other group also revealed that IL-21 regulates Th1 and Th17 effector responses during chronic H. pylori infection in a STAT1- and STAT3-dependent manner, therefore playing a major role controlling H. pylori infection and gastritis." (PMID 25349535, 2014). "In the present study, the expression levels of STAT3 and p-STAT3 were found to be higher in GAC than those in gastritis tissues, particularly in poorly differentiated GAC (P<0.05)." (PMID 24959290, 2014). "Augmented gp130/JAK/STAT3 activation has been reported in CagA-positive H. pylori dependent gastritis, thus arguing for STAT3 hyperactivation driven by CagA." (PMID 22312430, 2012). "Chronic atrophic gastritis often presents high expression levels of STAT3." (PMID 38698812, 2024). "Here we demonstrated that the gene associated with retinoid interferon-induced mortality 19 (GRIM-19) was severely depressed or lost in GC and chronic atrophic gastritis (CAG) tissues and its loss contributed to GC tumorigenesis partly by activating STAT3 signaling." (PMID 27167343, 2016). "Finally, we evaluated the nuclear expression of phosphorylated (p)-STAT3 protein in the gastric mucosa of gastritis patients according to the STAT3 genotypes." (PMID 26186918, 2015). "In gastritis, IL-6 mainly affects the damage and repair process of gastric mucosa by activating the JAK/STAT3 signaling pathway, regulating inflammatory response and immune cell differentiation." (PMID 41376630, 2025). "Empirical evidence suggests that Combined Formulas for Gastritis and DangguiShaoyao powder can effectively inhibit JAK1/STAT3 signaling pathways." (PMID 38698812, 2024). "We identified a class of TFH-like CD4+ T cells with the capacity to secrete IL-21 in the gastric mucosa of H. pylori-positive gastritis patients and demonstrated that the GITR/GITRL axis promoted IL-21+CD4+ T cell polarization via the STAT3 signal pathway." (PMID 34589088, 2021). "The expression levels of STAT3, p-STAT3, HIF-1α and VM were higher in patients with GAC (particularly in poorly differentiated GAC) than in those with gastritis (P<0.05)." (PMID 24959290, 2014). "The expression levels of STAT3, p-STAT3, HIF-1α and VM were assessed in 60 cases of patients with GAC and 20 cases of patients with gastritis on tissue microarrays by immunohistochemical methods." (PMID 24959290, 2014).
gastritis (continued). "Positive expression levels of STAT3, p-STAT3 and HIF-1α were significantly increased in the GAC specimens compared with the gastritis specimens, respectively (81.7 vs. 15.0, 58.3 vs. 5.0 and 63.3 vs. 10.0%; P<0.05)." (PMID 24959290, 2014). "The STAT3 signal pathway is essential for classical TFH cell differentiation, and we demonstrated here that GITR promoted TFH-like cell polarization via STAT3 signal in H. pylori-positive gastritis." (PMID 34589088, 2021). "In addition, the authors confirm that JAK1 and STAT3 are target genes of miR-1006b-5p and that the JAK1/STAT3 pathway plays a part in gastric inflammation (gastritis establishment) and carcinogenesis." (PMID 32260540, 2020). "The CagA+ H. pylori strains infection could increase signal transducer and activator of transcription 3 (STAT3) and mitogen-activated protein kinase (ERK1/2) activation in H. pylori-dependent gastritis." (PMID 25594045, 2014). "We found that the expression of the active form of STAT3 was significantly higher in H. pylori-positive gastritis (73.5%, 61/83) than in H. pylori-negative gastritis (50%, 35/70) (P = 0.003)." (PMID 25594045, 2014).
metastatic melanoma (21 papers, 2010 to 2025). A melanoma that has spread from its primary site to another anatomic site. "The ECHS1 gene, crucial for fatty acid beta-oxidation, interacts with STAT3 and has been linked to metastatic melanoma." (PMID 37844995, 2023). "STAT3 has been implicated in neoplastic progression with an increased contribution especially in metastatic melanoma." (PMID 22316093, 2012). "Furthermore, activation of STAT3 in Tregs was associated with decreased suppressive function in patients with metastatic melanoma." (PMID 38607233, 2024). "A 46-year-old male with metastatic melanoma developed pruritic firm erythematous papules on the face and bilateral neck 25 days after starting STAT3 inhibitor treatment." (PMID 40606688, 2025). "Clinical data from TCGA demonstrated that elevated E2F1, STAT3, and IL-6 correlate with infiltration of Th2, while simultaneously blocking Th1 in primary and metastatic melanomas." (PMID 39544930, 2024). "Signal transducer and activator of transcription 3 (STAT3) plays a part in decreasing TRAIL cytotoxicity in metastatic melanoma cells." (PMID 30157799, 2018). "Using Oncomine database, we found that the mRNA levels of FAK, Src, ERK1/2 and Stat3 increased, while the mRNA levels of PPARγ, C21orf34 (miR-125b host gene) and E-cadherin decreased in human metastatic melanoma." (PMID 28108732, 2017). "In metastatic melanoma, the expression of phosphorylated STAT3 is positively correlated with Bcl-xL expression." (PMID 23693134, 2013). "In human metastatic melanoma cell lines, PRMT5 was predominantly cytoplasmic, and associated with its enzymatic cofactor Mep50, but not STAT3 or cyclin D1." (PMID 24098663, 2013).
primary effusion lymphoma (21 papers, 2011 to 2025). A large B-cell lymphoma located in the body cavities, characterized by pleural, peritoneal, and pericardial fluid lymphomatous effusions and that is always associated with human herpes virus-8 (HHV-8). "Triptolide inhibited IL-6/STAT3 to reduce ascites formation and organ infiltration of primary effusion lymphoma." (PMID 36700235, 2022). "PI3K/AKT/mTOR, Wnt/β-catenin, and STAT3 also participated in quercetin-induced cell death in primary effusion lymphoma (PEL)." (PMID 33494431, 2021). "It has been previously reported that STAT3 is overexpressed in cutaneous angiosarcoma, pyogenic granuloma, Ewing's sarcoma, Kaposi's sarcoma and in primary effusion lymphomas." (PMID 21575192, 2011). "Activation of PIK3/AKT signaling and STAT3 via constitutive phosphorylation contribute to the growth and survival of primary effusion lymphoma (PEL) cells, a type of NHL driven by dual infection with Epstein Barr virus (EPV) and Kaposi sarcoma–associated herpesvirus (KSHV)." (PMID 33923680, 2021). "In hyperactive primary effusion lymphoma (PEL), quercetin reduced the release of cytokines and inhibited PI3K/Akt/mTOR and STAT3 pathway-induced autophagy, ultimately resulting in PEL cell death." (PMID 34025409, 2021). "In primary effusion lymphoma (PEL) cells, metformin inhibits both mTOR and STAT3 pathways by decreasing intracellular ROS levels." (PMID 29554968, 2018). "Quercetin exhibits anticancer effects in primary effusion lymphoma (PEL) by reducing cytokine release and inhibiting PI3K/Akt/mTOR and STAT3 pathway-induced autophagy, leading to PEL cell death." (PMID 41294806, 2025). "Additionally, quercetin inhibits PI3K/AKT/mTOR and STAT3 pathways specifically in primary effusion lymphoma (PEL) cells, leading to downregulation in the expression of the pro-survival cellular proteins such as c-FLIP, cyclin D1, and c-Myc." (PMID 35956766, 2022). "We have recently shown that quercetin, a flavonoid with anti-inflammatory and antioxidant properties and anti-cancer potential, was able to inhibit multiple pro-survival pathways activated in primary effusion lymphoma (PEL) cells, including STAT3, mTOR, and NF-κB, reducing cell survival." (PMID 31547402, 2019). "In this study, we used DNA or histone demethylating agents, 5-Azacytidine (5-AZA) or DS-3201 (valemetostat), respectively, to treat primary effusion lymphoma (PEL) cells, alone or in combination with AG490, a Signal transducer and activator of transcription 3 (STAT3) inhibitor." (PMID 38534772, 2024). "Indeed, down-regulation of the expression of HSF1/Hsp70 by STAT3 inhibitor AG490 suppressed Mcl-1 and led to the induction of apoptosis and autophagy in primary effusion lymphoma cells." (PMID 29541415, 2018). "It has been indicated that treating primary effusion lymphoma (PEL) cells with quercetin inhibits the PI3K/AKT and STAT3 pathways." (PMID 41195524, 2025). "It has been indicated that quercetin suppresses STAT3 and PI3K/AKT/mTOR pathways in primary effusion lymphoma (PEL) cells leading to downregulate the prosurvival cellular proteins expression, including cMyc, cyclin D1, and c-FLIP." (PMID 32175075, 2020).